RAC1 (Rac family small GTPase 1)
Diseases named in the same sentence as RAC1 in open-access papers (continued):
Sharing a sentence is not in itself a finding about the gene and the disease.
cancer (continued). "In cancer cells, signaling through S1PR1 leads to the activation of RAC1, SRC, PTK2/FAK1, as well as MAP kinases, and influences cell proliferation and survival in GBM." (PMID 34359681, 2021). "In the study in which DR5 promoted K-Ras cancer cell invasion and metastasis, it was suggested that constitutive signaling from DR5 promotes activation of a Rac1/PI3K/Akt signaling axis that increases migration and invasion." (PMID 33810241, 2021). "LIMK1 is a crucial component of Rac1/PAK1/LIMK1/cofilin signaling pathway, which is involved in several cancers." (PMID 34149814, 2021). "Following the progression towards cancer, our model shows an imbalance between the two opponents ras homolog family member A (RHOA) and ras-related botulinum toxin substrate 1 (RAC1) in favor of RAC1." (PMID 33578795, 2021). "After dividing dogs into groups according to breed we found upregulation of RAC1 together with GRB2 and CDH1 in carcinoma-solid compared to carcinoma-simple in mixed-breed dogs." (PMID 34679042, 2021). "Two stress-response kinases, p38 and JNK, have been recognized for their downstream role in RAC1 response to genotoxic stress, subsequent DDR, and resistance to cancer therapies." (PMID 32545340, 2020). "Invasive abilities of cancer cells are related to migration and many other factors, including expressions of MMP-2, MMP-9, Rac1, Rho A, and SOD2." (PMID 31772330, 2020). "MAPK signalling pathway (JUN, RAC1, MAPK8, MYC and FOS) and transcriptional misregulation in cancer (CDKN1A, MYC and FOXO1)." (PMID 32457348, 2020). "We have reviewed the distribution of patterns regarding the frequency of Ras-related C3 botulinum toxin substrate 1 (RAC1)-alteration(s) and their modes of actions in various cancers." (PMID 32545340, 2020). "In conclusion, taken together, the combination of Hst and Dox inhibited cancer cell’s growth and metastasis through cell cycle arrest, apoptosis, reduce cell migration, decrease HER2, Rac1, and MMP9 expression." (PMID 32458631, 2020). "In particular, diet-modulated miRNAs were able to target and interfere with several genes mainly involved in cancer signal transduction pathways (e.g., EGFR, RAC1, PLCG1, FOS, NRAS, SOS2, etc.)." (PMID 32911851, 2020). "Here, we present genetic and pharmacological evidence showing that Cdc42 and Rac1 GTPase signaling modulates a similar CTD Ser2 and Ser5 phosphorylation code in cultured human cancer cells." (PMID 32143485, 2020). "The Rac1/JNK pathway has been involved in doxorubicin-induced apoptosis of cardiomyocytes and human cancer cells." (PMID 31857649, 2019). "Rac1 mediates activation of the WRC and resulting actin polymerisation and can be hyperactivated in cancers." (PMID 31413787, 2019). "Compared to our previous findings, we found the opposite effect regarding the β-catenin/RAC1 complex; the fraction, ICC, Co-IP, and ChIP assay results confirmed that the role of KRT19 in different cancers is governed by differential mechanisms." (PMID 30650643, 2019). "RAC1 can undergo degradation only in an active GTP-bound state and this modification is somehow correlated to cancer progression." (PMID 31248017, 2019). "Small monomeric GTPases, like Ras and Rac1, are active when they are bound to GTP, and some studies reported that Rab-GTP was the functional type in cancer progression." (PMID 31175290, 2019). "Known cancer drivers NOTCH1, PPP6C, RAC1, EIF4G1, PIK3CA showed significant increase in frequency of SCNA in transition from PPOLs to HNSCC that correlated with their expression." (PMID 31427592, 2019). "•These findings suggest that MEK/ERK signaling through RAC1 and NRAS drives resistance to ER-stress in cancer cells." (PMID 29329780, 2018).
cancer (continued). "CDC42, RAC1, and RHOA are well characterized for actin reorganization, cancer invasion, and metastasis in various cancers but are still incompletely characterized in ESCC." (PMID 30327774, 2018). "Three cancer cell lines with up- or down-regulation of RCC2 were used to evaluate cell proliferation, apoptosis, Rac1 signaling and sensitivity to a group of nine chemotherapeutic drugs." (PMID 29321004, 2018). "Ki-RAS has four effectors that all play a role in cancer development: the MAPK pathway, the PI3K pathway, Ral guanine nucleotide dissociation stimulator (Ral-GDS), and RAC1." (PMID 28499439, 2017). "Our method revealed 3D clusters in all three RAS proteins (K/N/H-RAS), RAC1, BRAF, MAP2K1, and MAPK1 in a variety of cancer types." (PMID 28115009, 2017). "In turn, we demonstrated a significantly increased activation of the small G-protein RAC1, an effector of the WNT/PCP cascade proven to enhance motility and invasiveness of cancer cells." (PMID 28423716, 2017). "Tumor necrosis factor (TNF)-related apoptosis-inducing ligand (TRAIL) is known for specifically killing cancer cells, whereas in resistant cancers, TRAIL/TRAIL-R can promote metastasis via Rac1 and PI3K." (PMID 28212753, 2017). "Since both TGF-β responses are promoted by RAC1, it appears conceivable that RAC1 and RAC1b control TGF-β responses in cancer cells in an antagonistic manner with RAC1b acting as an endogenous inhibitor of RAC1." (PMID 28499439, 2017). "It is likely that the proliferation of cancer cells was more dependent on geranylgeranylated proteins such as RhoA, Rac1, etc., leading to greater sensitivity to the depletion of GGPP and inhibition of GGTase-Iβ expression than in the non-cancer cells." (PMID 28481295, 2017). "Zinc-treated cells exhibited the mesenchymal-like morphology and increased cancer cell motility with significant increase of activated FAK, Rac1, and RhoA." (PMID 27330411, 2016). "Rac1 is frequently activated or overexpressed in various types of cancer, including HCC, which plays a critical role in promoting cancer cell migration, invasion and metastasis." (PMID 26751560, 2016). "The functional effect of the P29S recurrent mutation is to induce a ‘fast cycling’ form of Rac1, as opposed to the more common gain-of-function mutations used in a laboratory setting which are modeled on activating Ras mutations found at high frequency in human cancers." (PMID 27104658, 2016). "Invasion of Matrigel by cancer cells is promoted by activation of cell-signaling factors such as ERK1/2 and Rac1 and by activation of cell-surface proteases." (PMID 27977780, 2016). "Considering the critical role of Rac1 in cancer, our results provide a novel mechanism for the different roles of GLS1 and GLS2 in tumorigenesis, particularly with respect to cancer metastasis." (PMID 26751560, 2016). "Published results suggest that blocking IQGAP1-CDC42 and IQGAP1-RAC1 complex formation will decrease the amount of active forms of CDC42 and RAC1 in carcinoma cells and thus reduce tumorigenesis." (PMID 27815503, 2016). "HeLa cells were used as an independent cancer-relevant, human cell line to test the full chemical series (R-naproxen, S-naproxen, and 6-MNA) for effect on Rac1 and Cdc42 activation using the G-trap assay." (PMID 26558612, 2015). "We studied how the Rho GTPases mediated SDF-1α effect, by demonstrating that RhoA and Rac1 were sequentially activated at different concentration of SDF-1α, thus, promoting different metastatic properties through the modulation of cancer cells phenotype." (PMID 26231656, 2015). "Appropriate amount of nestin enhances CDK5 function to suppress Rac1 and excessive nestin/CDK5 participates in multiple oncogenic pathways to promote cancer invasiveness." (PMID 25371063, 2015). "Rac1/Cdc42 overexpression also has been correlated with poor clinical outcome in NSCLC and other cancers." (PMID 26462147, 2015).
cancer (continued). "The second subgraph, which contains the largest number of component nodes, has its 95 nodes anchored to the known cancer proteins CTNNB1, APC, PTEN, TP63, MAPK4, MET, RAC1, and ROS1." (PMID 24516372, 2014). "Rac1 and ERK1/2 activation have been found to be a respond to the increased expression of MMPs in most cancer cells." (PMID 25136657, 2014). "Luciferase reporter assays demonstrated that miR-574-3p directly binds to the 3′ UTR of several target genes (such as RAC1, EGFR and EP300) that are components of ‘Pathways in cancer’." (PMID 23554959, 2013). "Altogether, these data suggest that nuclear Rac1 may play an important role in regulating cell proliferation and gene expression in cervical cells, and that the presence of Rac1 in the nucleus of cervical epithelial cells from pre-malignant lesions may contribute to cancer progression." (PMID 22443139, 2012). "Rac1 was reported to act as a downstream effect of PI3-K in several growth factor-stimulated pathways and to induce invasion and metastasis in cancer cells." (PMID 22454661, 2012). "Our results showed that the activity of Rac-1, one member of the Rho family, was suppressed by PS-A in RCC cells, indicating the potential mechanism for the inhibitory effects of PS-A to cancer cell migration." (PMID 22454663, 2012). "There is considerable evidence that wild type and mutant Rac1 and other Rho small GTPases can activate STAT3, especially within the context of cancer." (PMID 22606352, 2012). "Our results reveal that loss of miR-204 results in BDNF overexpression and subsequent activation of the small GTPase Rac1 and actin reorganization through the AKT/mTOR signaling pathway leading to cancer cell migration and invasion." (PMID 23285024, 2012). "Ras-related C3 botulinum toxin substrate 1 (Rac1), a small GTP-binding protein within the Rac subfamily of the Rho GTPase family, is a critical molecule that promotes cancer cell invasion and metastasis by regulating signal transmission and promoting cell polarity." (PMID 41188920, 2025). "In summary, the simple observation that an oncogene like HRasV12 could trigger the production of ROS via Rac1 and NADPH oxidase to transform cells has lead to a better understanding of the initiation and progression of cancers." (PMID 40328105, 2025). "CAV1 inhibition reduced expression of dormancy regulators E-cadherin, RAC1 and p21, enhanced cancer stemness markers, and disrupted downstream STAT3/P70S6K and AMPKα signalling pathways, prompting cancer cells to exit from dormancy and initiate autophagy-induced cell death." (PMID 40715090, 2025). "Super-EBS treatment inhibited Rac-1, Cdc42 and p-PAK1 expression levels in both cancer cell lines." (PMID 39781466, 2025). "Importantly, in multiple model systems, the Ras-driven pathway of oncogenic transformation was shown to depend on the function of RAC1 and its immediate downstream effector PAK1, representing a potentially exploitable vulnerability in a subset of cancers." (PMID 41154654, 2025). "Similarly, in the cancer cell line LS513, Rac1 levels surged from 0.5 before stretching to 1.5 pg mL−1 after stretching." (PMID 39887960, 2025). "The RAC1 oncogene resides on chr7p.22.1, which has not been recognized as a common amplicon in human cancers." (PMID 39941730, 2025). "However, the in vivo functional disparities between the two major RAC1 isoforms, RAC1B and the canonical RAC1A, and their therapeutic implications in cancer remain largely unexplored." (PMID 40548642, 2025). "Kaplan–Meier survival analyses showed that patients with RAC1-amp/gain tumors (n = 4005) in the TCGA Pan-Cancer cohort had significantly poorer overall survival (OS) and progression-free survival (PFS) when compared with patients having RAC1-diploidy tumors (n = 6053; log-rank test, p < 0.05)." (PMID 39941730, 2025).
cancer (continued). "Through the application of multiple immune infiltration algorithms, we observed a significant negative correlation between RAC1 expression and B lymphocyte score across various cancer types." (PMID 39898257, 2025). "The accumulation of oncogenic RAC1 in its GTP-bound state leads to uncontrolled cellular activities that may contribute to the initiation and progression of various types of cancer." (PMID 41034404, 2025). "Our investigation focused on RAC1, as it has been widely observed that its alternative splicing leads to RAC1B, a constitutive-active Ran GTPases which has been found to stimulate cancer cell proliferation, enhance epithelial-mesenchymal transition (EMT), and induce drug resistance." (PMID 39098911, 2024). "Similarly, several effector molecules, including CALD1, CDH1, FN1, FZD7, RAC1, STAT3, and WNT11, were downregulated in cancer cells treated with DBMSCs." (PMID 39768220, 2024). "Overall, RAC1 and RAC1B have similar effects on cancer cell phenotypes but utilize different pathways, suggesting they cannot substitute for each other, and both proteins should be investigated in the context of cancer." (PMID 39001533, 2024). "Rac1/NOX signaling is tightly controlled by the ubiquitin/proteasome-mediated degradation of the GTPase, as a decreased activity of the corresponding HACE1 ubiquitin ligase in eukaryotic model organisms or in tumor cell lines promotes cancer development." (PMID 38534316, 2024). "Active Rac1 destabilizes E-cadherin-mediated cell-cell adhesion by interacting with IQGAP1, and inhibiting Rac1 activity induces increased E-cadherin-mediated cellular adhesion in certain cancer cells." (PMID 38424547, 2024). "This complexity underscores the need for a deeper exploration of the non-canonical functions of these enzymes, as exemplified by the metabolic enzyme LDHA, which has been shown to activate Rac1 GTPase through non-traditional mechanisms to promote cancer." (PMID 38989284, 2024). "However, targeting Rac1-GTP activity using the Rac1-GEF inhibitor NSC23766 can effectively suppress the EMT and subsequent aggressive cancer cell behaviors." (PMID 38424547, 2024). "RAC1 is involved in invadopodia-mediated ECM degradation and drives locomotion by regulating patellar pseudopodia formation, adhesion plaques, and MMP expression, which is an activity required for cell migration/invasion during cancer metastasis." (PMID 37202394, 2023). "Therefore, we withdrew the supplements to test the effect of EGF alone on the activity of RAC1 and CDC42 in these cells and compared the responses with those of the cancer cells." (PMID 37057894, 2023). "Here we describe that a wide spectrum of human cancers harbors a co-amplification of CBX3 gene with either EGFR or RAC1, which yields a statistically significant increase of both mRNA and protein levels of CBX3, EGFR and RAC1." (PMID 37633946, 2023). "Interestingly, we have also found that in cancer samples where CBX3 gene is amplified, there is also a statistically significant increase of RAC1 mRNA expression regardless the tumor tissue of origin." (PMID 37633946, 2023). "Recent work suggested a potential collaboration between Rac1 and the CCL2-CCR4 axis in promoting cell migration and cancer metastasis, emphasizing the potential significance of statins in reducing Rac1 prenylation and thereby function toward enhancing HNSCC treatment outcomes." (PMID 37568764, 2023). "RAC1 and RAC1B are highly expressed in certain types of tumors and can promote cancer progression." (PMID 37059183, 2023). "Interestingly, in none of the diverse cancer types analyzed, including TCGA Pan Cancer Atlas samples, we observed an increase of CBX3 transcripts compared to tumor samples which are diploid for either EGFR or RAC1." (PMID 37633946, 2023). "In addition, PAK1 is a key downstream effector of Small Rho GTPases Rac1 and CDC42 and which was related to cell morphogenesis, motility, mitosis, survival, and angiogenesis in various cancers." (PMID 36675278, 2023).
cancer (continued). "The Ras-related C3 botulinum toxin substrate 1 (RAC1), a small signaling GTPase, has been found to be indirectly regulated by CBX3 during tumor progression, and its gene has been recently found to be amplified in cancer." (PMID 37633946, 2023). "Because CCDC85A upregulated TGFβ in cancer cells under the hypoxic conditions, it may promote EMT and activate Rac1/CDC42." (PMID 37534255, 2023). "Since mutant Rac1 is specifically expressed on cancer cells and is important for the perpetual growth and survival of tumor cells, it is a promising target candidate for TCR gene therapy, a methodology that equips patient T cells with anti-cancer specificity." (PMID 36875127, 2023). "Inhibition of protein SUMOylation induces autophagic-mediated cancer cell death through the upregulation of tribbles pseudokinase 3 (TRIB3) and inhibits cancer cell invasiveness through the activation of the small GTPase rac1." (PMID 35465332, 2022). "The 864 mutated genes (410 in newly generated subclones; 454 in eliminated subclones) were enriched for annotations related to several cancer-related pathways, including “FGFR2 mutant receptor activation”, “RAC1 GTPase cycle”, “Signaling by MAPK mutants”, etc.." (PMID 35260570, 2022). "Therefore, extracellular calcium influx through Piezo1 upregulates PKA, ERK, Rac1, and ROCK activities which have the potential to promote cancer cell survival, proliferation, and migration." (PMID 35646889, 2022). "Active Rac1-GTP in AML promotes pro-survival signals through different pathways and enhances the production of reactive oxygen species (ROS) and inflammation, which renders the surroundings preferable for cancer development." (PMID 36009428, 2022). "Although the activation of RAC1 responds to various stimuli, RAB4A has not been previously identified as an upstream regulator for RAC1, particularly in the progression of cancer." (PMID 36307864, 2022). "Rac1 is known to be a key regulator in the multifaceted process of cancer cell migration and invasion, but irrespective of its pertinent role, clinically validated selective Rac1 inhibitors are not available to date." (PMID 36377725, 2022). "Our laboratory has recently demonstrated that CAV1 increases migration, invasion, and metastasis of cancer cells lacking E-cadherin in a manner dependent on Y14 phosphorylation and activation of a Rab5/Rac1 signaling axis." (PMID 35740528, 2022). "In addition, RAC1 and CDC42 are correlated with cancer metastasis, upregulating the PI3K signaling pathway to promote the migration and invasion of various types of cancer, including HCC." (PMID 36348464, 2022). "Moreover, ASPN upregulates CD44 expression and activates Rac1 via interaction with CD44 on the cell membrane, which also increases cancer cell spreading." (PMID 34379869, 2022). "However, overactivation of the RHO subfamily such as RAS-related C3 botulinum toxin substrate 1 (RAC1) and cell division cycle 42 homolog (CDC42) are also known to promote the hyperactivation of critical signaling cascades leading to cancer." (PMID 33684443, 2021). "RAC1 is a key regulator of multiple oncogenic pathways including activation of mTORC1/2, PAK1/2/3 and MAPK signaling, which plays an important and critical role in cancer metastasis and cell survival." (PMID 34803511, 2021). "In NSCLC, inhibiting Rac1 activated during EMT can inhibit the dynamic transformation between cancer stem/progenitor cells (CS/PC) and non-CS/PC." (PMID 34079763, 2021). "Overactivation of Rac1 has been found in various human cancers, including non-small-cell lung cancer." (PMID 33758209, 2021). "RAC1, a key regulator of multiple oncogenic pathways including mTORC1/2 and PAK1/2/3 among others 22 is emerging as a significant therapeutic target in different cancers." (PMID 34803511, 2021). "In cancer therapy a drug candidate named "Rhosin" has been designed, which effectively inhibits the Rho-subfamily of Rho GTPases, without affecting Rac1 or Cdc42." (PMID 33906663, 2021).